SNORD115-47 (small nucleolar RNA, C/D box 115-47)
Synonyms: HBII-52-47
Gene: Small nucleolar RNA gene on chromosome 15 (25,268,466 to 25,268,551, forward strand). Ensembl gene ENSG00000212528.
Homologues: Orthologues: chimpanzee SNORD115 (100% identical), macaque SNORD115 (85% identical). Paralogues in human: SNORD115-16 (67% identical), SNORD115-7 (67% identical), SNORD115-11 (66% identical), SNORD115-13 (66% identical), SNORD115-14 (66% identical), SNORD115-29 (66% identical), SNORD115-30 (66% identical), SNORD115-34 (66% identical), SNORD115-35 (66% identical), SNORD115-36 (66% identical), SNORD115-39 (66% identical), SNORD115-43 (66% identical), and 37 more.